BRAF (B-Raf proto-oncogene, serine/threonine kinase)
Diseases named in the same sentence as BRAF in open-access papers (continued):
Sharing a sentence is not in itself a finding about the gene and the disease.
melanoma (continued). "There is also a “rule of thumb” in melanoma, i.e., only one oncogene can be mutated in the same pathway, meaning that these three mutations (KIT/NRAS/BRAF) are mutually exclusive." (PMID 40361349, 2025). "Our results highlight that mitfa expression does not directly reflect Mitfa activity, as mitfa-target genes are more highly expressed in BRAF-positive melanoma despite lower mitfa expression compared to GNAQ-positive melanoma." (PMID 40950146, 2025). "Preclinically, BRAF inhibition suppresses IL-1α production in melanoma cell lines, implying a potential indirect role in TLS modulation." (PMID 40475020, 2025). "For that, we expressed PAGFP-RBD (of BRAF) and PAmCherry-NRas in 108T melanoma cells, imaged them, and analyzed their mutual organization using the same approach." (PMID 41373795, 2025). "The study was conducted in a mouse model with BRAF and NRAS mutations, as well as wild-type melanoma xenografts and allografts of highly metastatic melanoma." (PMID 41178942, 2025). "Together, these data suggest that the canonical GEF activity of PREX2 counteracts MAPK inhibition in BRAF PTEN melanoma." (PMID 39636745, 2025). "The cytoskeletal effector MARCKS, upregulated in BRAF inhibitors-resistant melanoma, is critical for cell migration and metastasis." (PMID 40332392, 2025). "BRAF gene amplification occurs when melanoma cells increase the number of BRAF gene copies, leading to an overexpression of the mutant BRAF V600E protein." (PMID 40872623, 2025). "In patients with BRAFV600E/K mutant advanced melanoma, the addition of pembrolizumab to BRAF and MEK inhibitors substantially improved PFS and OS and resulted in more durable responses." (PMID 40635600, 2025). "This study investigates metabolic changes induced by dual BRAF/MEK inhibition in a BRAFV600E-mutant murine melanoma model using magnetic resonance spectroscopy (MRS), optical redox imaging (ORI), and biochemical assays." (PMID 39984334, 2025). "For example, the X-ray crystallographic determination of the BRAF kinase structure revealed the molecular mechanism of its activation in melanoma, leading to the development of vemurafenib, a targeted therapy for BRAF-mutant melanoma." (PMID 41209584, 2025). "It is noteworthy that among the drugs we identified, Encorafenib is an antitumor agent used for melanoma that acts by inhibiting the BRAF gene." (PMID 40165336, 2025). "Since BRAF is the most abundant driver mutation in melanoma, we also analyzed the PLK1 expression in patients with melanoma harboring BRAF mutations." (PMID 41284701, 2025). "Within the melanoma microenvironment, aberrant ERK signaling—driven by oncogenic BRAF mutations—induces MITF degradation via a ubiquitin-mediated proteasomal pathway, contributing to dysregulated melanocytic lineage commitment and tumor progression." (PMID 40427124, 2025). "For patients with BRAF-mutant stage III melanoma, current treatment guidelines recommend adjuvant therapy using BRAF inhibitors such as dabrafenib or vemurafenib in combination with the MEK inhibitor trametinib." (PMID 41148289, 2025). "The results of this PMS in real-world clinical practice in Japan did not reveal any additional safety concerns compared with clinical trials of the combination treatment of encorafenib plus binimetinib in patients with BRAF-mutant malignant melanoma." (PMID 39918770, 2025). "Systemic treatments, including immunotherapy and BRAF-targeted therapy, have shown improved outcomes in selected patients with melanoma brain metastases." (PMID 41552174, 2025). "In this study, we applied two-color PALM and a combination with dSTORM (all in TIRF mode) to resolve the mutual nanoscale organization of NRas, PI3K and BRAF at the PM of 108T melanoma cells." (PMID 41373795, 2025). "Secondary mutations in NRAS, observed in 20%–30% of resistant cases, enable melanoma cells to bypass BRAF blockade by reactivating the MAPK/ERK signaling cascade, facilitating continued cell proliferation." (PMID 39897423, 2025).
melanoma (continued). "Reported evidence indicate that AMBRA1 deficient mice models represent accelerated tumor growth, invasiveness, and metastasis in BRAF/PTEN melanoma phenotype via increased activity of Focal Adhesion Kinase 1 (FAK1)." (PMID 40248706, 2025). "Pharmacological AR inhibition (e.g., with enzalutamide) restores sensitivity to BRAF/MEKi in both sexes thus enhances treatment efficacy, and providing a compelling rationale for combination therapy approaches in melanoma." (PMID 40361336, 2025). "The combination of BRAF/MEK inhibitors is now the standard of care in advanced melanoma harboring BRAF V600E-mutant due to the improved survival relative to BRAF inhibitor monotherapy." (PMID 40592836, 2025). "Binimetinib, which is FDA-approved for use in combination with encorafenib for BRAF V600E or V600K mutant melanoma, was chosen for its established clinical efficacy and capability for clinical translation." (PMID 41282105, 2025). "Recent reports have proposed that RSK1/2 are potential therapeutic targets in melanoma with constitutive MAPK activation to overcome resistance to BRAF and MEK inhibitors." (PMID 39658088, 2025). "Resistance to BRAF and MEK inhibitors in BRAFV600E melanoma has been linked to compensatory activation of cAMP-dependent signaling networks, involving PKA, and CREB." (PMID 40719625, 2025). "Studies have shown that PTEN loss is associated with poor survival in stage III melanoma, and genomic alterations in PTEN are linked to protein loss, potentially predicting intrinsic resistance to BRAF inhibitor therapy." (PMID 40129883, 2025). "Inhibition of PD-1 or PD-L1 enhances the efficacy of both BRAF inhibitor monotherapy and dual BRAF/MEK inhibition in BRAFV600 melanoma mouse models." (PMID 40361336, 2025). "In patients with advanced BRAF(V600)-mutant melanoma, spartalizumab has been evaluated in combination with BRAF and MEK inhibitors." (PMID 40725830, 2025). "The advent of immune checkpoint inhibitors (ICIs) and targeted therapy with BRAF/MEK inhibitors (BRAFi/MEKi) has profoundly transformed the landscape of melanoma treatment, leading to marked improvements in outcomes for patients with metastatic melanoma (MM)." (PMID 40821396, 2025). "This subtype is associated with a lower mutational burden compared to other melanoma types, which can complicate treatment strategies, as TWT melanomas often do not respond well to targeted therapies that are effective in BRAF or NRAS mutant melanomas." (PMID 40867277, 2025). "Consistently, treatment with the MAPK inhibitor U0126 abolished the interaction between ERK and TRIM63, and inhibited TRIM63 phosphorylation in melanoma cells carrying BRAF V600E." (PMID 41315179, 2025). "In this regard, a phase I/II trial study using Navitoclax in combination with dabrafenib and trametinib is recruiting unresectable or metastatic patients with BRAF mutant melanoma (ClinicalTrials.gov, NCT01989585)." (PMID 40721981, 2025). "The present study aimed to determine the selective effects of BRAF V600E inhibitor on focal adhesion in melanoma cells with respect to their phenotypic reprogramming." (PMID 40636307, 2025). "Despite advances in the treatment of melanoma with BRAF and MEK inhibitor combinations and immune checkpoint inhibitors, the development of resistance is very common." (PMID 40135438, 2025). "SIRT5 is responsible for the proliferation and survival of BRAF-mutant melanoma cells through repressing apoptosis as a consequence of chromatin modification and expression of survival factors such as MITF and c-Myc." (PMID 39935431, 2025). "The drug resistance exhibited by BRAF mutant patients treated with BRAFi + MEKi and those undergoing immunotherapy is a formidable obstacle in melanoma management." (PMID 40331942, 2025). "This dual role raises questions about its influence on treatment response and potential contribution to therapy resistance in BRAF/MEK-treated melanoma." (PMID 40659866, 2025).
melanoma (continued). "In contrast to monotherapy with BH3-mimetics, the combination of Mcl-1 inhibitors with Bcl-2 inhibitors showed promising activities against BRAFV600E-mutant and BRAF-wildtype melanomas." (PMID 39935431, 2025). "The time between the pathological diagnosis and BRAF testing was longer for early-stage melanoma, which suggested a high proportion of the stage I tumours were tested on recurrence." (PMID 40902091, 2025). "Imatinib, targeting c-KIT and PDGFR mutations, demonstrates therapeutic benefit primarily in acral and mucosal melanoma subtypes, though with lower response rates than BRAF-directed therapies." (PMID 41302945, 2025). "ARV-SNEP exhibited superior anticancer efficacy, anti-migration, and pro-apoptotic effects over free ARV-825 in BRAF inhibitor-resistant melanoma cells at nanomolar drug concentrations." (PMID 40284496, 2025). "CDC20 is also deemed as a therapeutic target, for its inhibitors show efficacy in preclinical melanoma models, including the ability to overcome BRAF inhibitor resistance." (PMID 41425556, 2025). "SIRT1 also deacetylates Beclin 1, leading to upregulated autophagy and degradation of E-cadherin accompanied by increased metastatic potential of BRAF-mutant melanoma cells." (PMID 39935431, 2025). "In younger individuals, superficial spreading melanoma (SSM) and nodular melanoma (NM) are the most prevalent melanoma subtypes, frequently driven by BRAF mutations." (PMID 40227833, 2025). "BRAF-mutant melanoma cells can be rescued from BRAF inhibitor-induced growth arrest by various RTK ligands." (PMID 40332392, 2025). "For patients with BRAF-mutant melanoma, BRAF/MEK inhibitors induce rapid responses, although they tend to be less durable than immunotherapy." (PMID 40984902, 2025). "In vitro proliferation of BRAFV600E melanoma cells was recently shown to be inhibited by PROTACs generated from the BRAF inhibitor BI882370." (PMID 39898116, 2025). "More recently, GNF-7 and its derivative SIJ1227 were shown to strongly decrease the proliferation, migration, and invasion of BRAF-mutant melanoma cells." (PMID 40805174, 2025). "There are currently three FDA-approved BRAF/MEK inhibitor combinations approved for advanced melanomas." (PMID 40564107, 2025). "They analyzed ctDNA levels of BRAF and NRAS mutations in plasma samples from 29 advanced melanoma patients who exhibited disease progression after 12 weeks of anti-PD-1 therapy." (PMID 39859576, 2025). "The anti-PD-1 monotherapy demonstrated significant efficacy, with nivolumab achieving a three-year OS rate of 51.2% compared to 21.6% for dacarbazine in BRAF wild-type melanoma." (PMID 41527622, 2025). "An active targeted liposome encapsuled with anti-BRAF siRNA (siBraf) was developed in melanomas treatment." (PMID 39891180, 2025). "Recent phosphoproteomic studies have identified PFKFB2 as a downstream phosphorylation substrate of RSK in BRAF-mutant melanoma cells." (PMID 40872623, 2025). "Thebest known reference for a drug rest in melanoma therapy isthe BRAF/MEK pathway inhibitor vemurafenib, which is still the mosteffective drug for patients carrying this mutation." (PMID 40621031, 2025). "This national retrospective cohort study identified all new melanomas and molecular BRAF testing in England diagnosed from 2016 to 2021 using population-based data from the National Disease Registration Service." (PMID 40902091, 2025). "Melanoma cells escaping BRAF/MEKi or ICIs frequently exhibit altered metabolic states that impact chromatin accessibility, histone modifications, and drug tolerance." (PMID 40573249, 2025). "To validate our biochemical data and expand its applicability to melanoma, we examined RAC1P29S activity in IGR1 human melanoma cells, which harbor both the RAC1 P29S and BRAF V600K mutations endogenously." (PMID 41034404, 2025). "BRAF inhibitors downregulate the expression of various NK-cell-activating ligands (NKALs) on the surface of melanoma cells, dampening NK cell attack." (PMID 40058234, 2025).
melanoma (continued). "In melanoma, BRAF inhibition was shown to up-regulate oxidative phosphorylation through increased PGC1α and MITF expression." (PMID 40950224, 2025). "Mutation frequency analysis also revealed recurrent abnormalities in genes such as TTN, MUC16, and BRAF, which correspond to their recognized functions in melanoma development." (PMID 41150769, 2025). "Both D + T and anti-PD1s are standard of care options for the adjuvant treatment of stage III and resected stage IV BRAF mutant melanoma." (PMID 40758471, 2025). "Among these combinations, combinations of mitogen-activated protein kinase (MEK) inhibitors and BRAF inhibitors have become the standard treatment for melanoma patients." (PMID 40063190, 2025). "Autophagy is regulated by SIRT6 in BRAF-mutant melanoma dependent on the stage of the melanoma cells, and SIRT6 expression correlated with the expression of the autophagy factors LC3 and p62." (PMID 39935431, 2025). "For instance, B-Raf proto oncogene Serine/Threonine protein kinase (BRAF) induces ER stress and up-regulates autophagy, rendering melanoma cells resistant to chemotherapy." (PMID 40497999, 2025). "Patient 2, a male in his 70s with BRAF-wildtype melanoma, received multiple treatments, including stereotactic radiosurgery for a left frontal brain metastasis and pembrolizumab, over several years." (PMID 40264106, 2025). "GSDME expressed by the pyroptostic cell the combined treatment of BRAF and MEK inhibitors in melanoma can elevate the amount of T cells and DCs, while GSDME-deficient melanoma exhibited less HMGB1 release and BRAFi and MEKi resistance." (PMID 40064873, 2025). "We observed that BRAF-mutant melanoma cells expressing an active AKT1 mutant (E17K) displayed elevated levels of focal adhesion (FA) factors and phosphorylated focal adhesion kinase (P-FAK)." (PMID 39922199, 2025). "Trametinib is an ERK/MAPK inhibitor, historically used in BRAF-mutant melanoma and NSCLC and in NF1-related nervous system tumors recently." (PMID 40052442, 2025). "At our melanoma center, we often observe that upon treatment with BRAF/MEK inhibitors, vitiligo develops and progresses during treatment, and persists even after the end of treatment." (PMID 39834728, 2025). "In another study, OncomineTM Pan-Cancer Cell-Free Assay, a 52-gene panel, was performed on a tumor and was compared to its application on ctDNA plasma samples from 22 advanced melanoma patients before first-line treatment (BRAF/MEKi or ICI)." (PMID 39859576, 2025). "BRAF and MEK inhibition combinations have proven to work well in BRAF-mutated melanomas, but they have limited efficacy in this subtype." (PMID 40331942, 2025). "In BRAF-melanoma xenograft mouse and zebrafish models, both HiGom and AgGom significantly reduce tumor growth and melanoma cell proliferation." (PMID 41271646, 2025). "We observed that CD8+ T cells were relatively scarce in BRAF/MEKi‐insensitive, on‐therapy regrowing melanoma tumors, but abundant in BRAF/MEKi‐sensitive, on‐therapy regressing tumors, as quantified in vehicle‐treated, regressing, and regrowing tumors." (PMID 40847444, 2025). "Recent studies on copper ionophore disulfiram have demonstrated that, by targeting mitochondrial function, this compound can suppress melanoma with resistance to BRAF inhibitors." (PMID 41304533, 2025). "Mutations in BRAF V600E or NRAS, common drivers in melanoma, can paradoxically induce senescence in melanocytes during early transformation stages." (PMID 40926366, 2025). "We describe the case of a patient with a history of CLL on surveillance who was subsequently found to have recurrent Stage IIIC melanoma who appeared to test positive for both an NRAS G12D and a BRAF V600E mutation." (PMID 39940799, 2025). "Spatial transcriptomic analysis was performed on a selected number of samples extracted from a larger cohort of acral melanoma patients to assess the immune landscape in relation to BRAF expression levels." (PMID 41002140, 2025).
melanoma (continued). "Adjuvant treatment of stage III resected melanoma with BRAF/MEK inhibitors provided a 71% OS at 8 years and a median progression-free survival (PFS) of 93.1 months." (PMID 40904502, 2025). "Binimetinib 45 mg orally twice daily, in combination with encorafenib (also known as LGX818), has received marketing approval in several jurisdictions for the treatment of patients with BRAF V600E or V600K mutant melanoma." (PMID 39887964, 2025). "Transcriptional programs enriched in BRAF- versus GNAQ-driven melanoma overlap with specific melanocyte progenitor populations." (PMID 40950146, 2025). "Several melanoma therapies, including BRAF/MEK inhibitors and radiation, induce a senescence‐like state in both tumor and stromal cells." (PMID 40926366, 2025). "Mutant BRAF genes are commonly expressed in a majority of melanomas, indicating their significant role in melanocyte biology and disease pathology." (PMID 40277680, 2025). "The impact of tovorafenib on in vivo antitumor activity was assessed in an AGK::BRAF fusion melanoma PDX model and in two NF1-LOF models, including an ERMS PDX and the MeWo melanoma xenograft." (PMID 40111124, 2025). "In a single-dose pharmacokinetic–pharmacodynamic (PK–PD) study, mice bearing AGK::BRAF fusion melanoma PDX tumors were orally administered tovorafenib at 17.5 or 25 mg/kg." (PMID 40111124, 2025). "Recurrent mutations, including the activation of oncogenes (BRAF, NRAS) and loss of tumor-suppressors (PTEN, CDKN2A), drive the early stages of melanoma formation." (PMID 41286309, 2025). "Chapman and colleagues demonstrated impressive response rates with the BRAF inhibitor vemurafenib in BRAF V600E-mutant melanoma." (PMID 41614813, 2025). "While KRAS mutations in cutaneous melanoma occur less frequently than BRAF or NRAS mutations, KRAS-linked signaling has garnered attention in other malignancies and exhibits the potential to influence melanoma cell proliferation and phenotypic plasticity." (PMID 40607411, 2025). "Fitness penalties have been demonstrated in BRAF-resistant melanoma and EGFR-resistant metastatic colorectal cancer but have not been defined during the evolution of resistance to common cytotoxic therapies like platinum chemotherapy." (PMID 40299825, 2025). "The upregulation of MHCA and decreased expression of PD-L1 suggest an improved immune therapy response in BRAF-mutant melanoma treated with GZ17-6.02." (PMID 39935431, 2025). "The challenge of using BRAF and MEK inhibitors in treating patients with BRAF-mutant melanoma arises from the issue of acquired resistance." (PMID 40515636, 2025). "These alterations enable melanoma cells to bypass BRAF inhibition, leading to sustained signaling that promotes tumor growth and survival." (PMID 39897423, 2025). "Binimetinib, in combination with encorafenib, has received marketing approval in several jurisdictions for the treatment of patients with BRAF V600E or V600K mutant melanoma." (PMID 39887964, 2025). "In melanoma, it has been shown that this gene is regulated transcriptionally by MITF and that its expression is associated with resistance to BRAF inhibition." (PMID 39658088, 2025). "The factors associated with resistance included elevated platelet-to-lymphocyte ratio (PLR), the presence of acral/mucosal melanoma, BRAF mutant disease, low globulin levels and ≥3 metastatic sites." (PMID 41010951, 2025). "Targeting glutamine transport can suppress melanoma growth and represents a potential therapeutic target for both BRAF(WT) and BRAF(V600E) melanoma." (PMID 40565936, 2025). "Mutant BRAF is a classic driver oncogene with a high prevalence in melanoma (more than 50%), thyroid cancers (50%), colorectal cancers (15%), and NSCLCs (5–8%)." (PMID 40332392, 2025). "BRAF-mutant melanomas that emerged from an aged TME, known to be less sensitive to BRAFi + MEKi, also upregulated NR2F1 protein levels." (PMID 40955663, 2025).